BCAT2 (branched chain amino acid transaminase 2)
Diseases named in the same sentence as BCAT2 in open-access papers (continued):
Sharing a sentence is not in itself a finding about the gene and the disease.
glioma (5 papers, 2018 to 2022). A benign or malignant brain and spinal cord tumor that arises from glial cells (astrocytes, oligodendrocytes, ependymal cells). "The function of BCAT1 and BCAT2 have been widely reported in various types of cancers, such as gliomas and chronic myeloid leukaemia." (PMID 35326233, 2022). "In particular, D-2HG can inhibit BCAT1 and BCAT2, inducing glioma cells dependent on glutaminase and more sensitive to oxidative stress compared to IDH wild-type glioma cells." (PMID 33923299, 2021). "Previous studies have suggested that BCAT2 supports glioma growth by maintaining glutamate biosynthesis and redox homeostasis." (PMID 31784505, 2019). "In gliomas, 2HG, which is a competitive inhibitor of multiple α-KG-dependent dioxygenases, produced by mutant-IDH1, has been found to inhibit BCAT1 and BCAT2." (PMID 33367952, 2021).
lung cancer (5 papers, 2020 to 2025). A malignant neoplasm involving the lung. "Conversely, in a limited number of tumors, such as pancreatic and lung cancers, BCAT2 appears to play a more significant role." (PMID 40274762, 2025). "In non–small-cell lung cancer (NSCLC), BCAAs are used as nitrogen sources, and the dysfunction of the enzymes branched-chain amino acid transaminase (BCAT) 1 and BCAT2, which are responsible for BCAA usage, impairs NSCLC tumor formation." (PMID 38305803, 2024). "The mild reduction of BCAT2 was also found in metastatic lung cancer tissues but without statistical significance due to variation between patients." (PMID 34646394, 2021).
acute myeloid leukemia (4 papers, 2022 to 2025). Acute myeloid leukemia (AML) is a group of neoplasms arising from precursor cells committed to the myeloid cell-line differentiation. "Emerging studies have shown that the BCAA metabolic enzymes BCAT1 and BCAT2 are aberrantly activated and functionally required for malignant tumors such as chronic myeloid leukemia, acute myeloid leukemia, and PDAC." (PMID 36341436, 2022). "In acute myeloid leukemia (AML), METTL16 drives tumor development by promoting the expression of branched-chain amino acid (BCAA) transaminases BCAT1 and BCAT2, reprogramming BCAA metabolism." (PMID 41256854, 2025).
melanoma (4 papers, 2023 to 2025). A malignant, usually aggressive tumor composed of atypical, neoplastic melanocytes. "BCAT2 promotes melanoma progression by epigenetically regulating FASN expression through the P300‐dependent histone acetylation." (PMID 39778006, 2025). "To assess Notch1 and Notch2 activity, we used SNAP23 and BCAT2, two downstream targets of Notch1 and 2, respectively, that we identified by a microarray analysis of human melanoma cells in which each Notch receptor was inhibited by a specific shRNA." (PMID 39491031, 2024). "We found that individuals with high expression of BCAT2 showed a significant poorer response rate (p = 0.04) in GSE35640 cohort (melanoma)." (PMID 36642843, 2023). "Branched‐chain amino acid transaminase 2 (BCAT2) is an oncogene in melanoma." (PMID 39778006, 2025). "The expression of branched-chain amino acid transaminase 2 (BCAT2) also affects the levels of FASN and ACLY, promoting De Novo lipogenesis and facilitating melanoma progression." (PMID 38921444, 2024).
bladder cancer (3 papers, 2023 to 2025). "In this context, the BCAT2 expression level was even tested in forecasting a curative effect of bladder cancer-guided immunotherapy." (PMID 39452702, 2024). "Ahead of immunotherapy, subcutaneous bladder cancer model was built by BCAT2 KD and control murine cell lines." (PMID 36642843, 2023). "However, recent studies on bladder cancer have shown the immunosuppressive role of BCAT2 through its inhibitory impact on cytotoxic lymphocyte recruitment by restraining activities of proinflammatory cytokine/chemokine-related pathways and the T-cell chemotaxis pathway." (PMID 39452702, 2024). "Through analyzing tumor microenvironment (TME)‐related indicators, it is validated that BCAT2 shapes a noninflamed TME in bladder cancer." (PMID 36642843, 2023). "By means of a 34‐cytokine and chemokine immunoassay panel, we revealed that chemokines including CCL3, CCL4, CCL5, CXCL9, and CXCL10, are robust negative correlated with expression of BCAT2 in human and murine bladder cancer cell." (PMID 36642843, 2023). "Additionally, the outcome of T‐cell‐mediated cancer cell killing assay (without T cells group) can infer that BCAT2 plays an oncogenic role in bladder cancer." (PMID 36642843, 2023).
gastric cancer (3 papers, 2022 to 2026). A primary or metastatic malignant neoplasm involving the stomach. "To identify the functional effects of BCAT2 in gastric cancer cell lines, we transfected the BCAT2 overexpression plasmid into AGS and HGC-27 cells." (PMID 35265615, 2022). "In addition, dysregulation of BCAT2 correlates with the overall survival time of gastric cancer patients, and this study contributes to the potential treatment of gastric cancer." (PMID 38028625, 2023). "Relationships between BCAT2 expression and clinical-pathological parameters in gastric cancer." (PMID 35265615, 2022).
glioblastoma (3 papers, 2023 to 2024). The most malignant astrocytic tumor (WHO grade IV). "IDH wild-type patient-derived (A11, S2, SP20, and A25) and established human (U87 and U251) and rat (C6) glioblastoma cell lines showed variable concentrations of BCAT1 and BCAT2." (PMID 37885806, 2023).
liver cancer (3 papers, 2021 to 2025). An epithelial or non-epithelial malignant neoplasm that arises from the liver. "We show that BCAT2 is involved in system Xc– inhibitor-induced ferroptosis in liver cancer cells." (PMID 33097833, 2021). "Thus, our results demonstrate that BCAT2 serves as a suppressor of ferroptosis, and contributes to the core metabolic signaling pathways involved in liver cancer ferroptosis." (PMID 33097833, 2021). "Consistent with our recent findings in pediatric liver cancer, we also observed that CM272 markedly reduced the expression of amino acid metabolic enzymes (ASNS, PYCR1, BCAT2), as well as genes involved in the serine pathway (PHGDH, PSPH, PSAT1)." (PMID 39810240, 2025).
prostate carcinoma (3 papers, 2025 to 2026). A carcinoma that arises from epithelial cells of the prostate gland. "In prostate cancer, BCAT2 physically interacted with PCBP1 at position leucine 239 through hydrogen‐bond networking, and their complex cooperatively activated the PI3K/AKT signaling pathway." (PMID 41457818, 2026).
Arrhythmia (2 papers, 2022 to 2023). Any cardiac rhythm other than the normal sinus rhythm. "Arrhythmia inducibility studies in Langendorff-perfused hearts showed an increased incidence of inducible arrhythmias in Bcat2p.Q300*/p.Q300* mice compared to Bcat2+/+ (50% vs. 11.1%, respectively), the majority of which were non-sustained." (PMID 34142125, 2022). "Similarly, arrhythmias have as yet not been reported in BCAT2 mutation carriers, but our results suggest that an in-depth cardiac electrophysiological investigation and follow-up could be beneficial for these patients as well as individuals suffering MSUD." (PMID 34142125, 2022).
diabetic cardiomyopathy (2 papers, 2021 to 2025). Diabetic cardiomyopathy is a disorder of the heart muscle in people with diabetes. "Increased plasma and myocardial BCAAs have also been found in a diabetic cardiomyopathy mouse model with reduced expression of BCAT2, where pyridostigmine induced BCAA metabolism and clearance and attenuated the formation of myocardial scar tissue." (PMID 40759793, 2025). "In addition, BCKDHA phosphorylation and BCKDK protein expression were increased, whereas BCAT2 and PP2Cm protein expression was decreased in diabetic cardiomyopathy mice." (PMID 34084135, 2021). "The real-time PCR results showed that BCAT2 and PP2Cm mRNA levels were lower and that BCKDK mRNA levels were higher in diabetic cardiomyopathy mice than in control mice." (PMID 34084135, 2021).
maple syrup urine disease (2 papers, 2023 to 2025). An autosomal recessive inherited disorder caused by mutations in the BCKDHA, BCKDHB, DBT, and DLD genes. "The challenge, as with BCAT2, is the shadow of maple syrup urine disease—a condition where BCKDH is overly active or BCKDK is deficient, leading to continuous BCAA breakdown and dangerously low BCAA levels in the body." (PMID 41502503, 2025).
non-small cell lung carcinoma (2 papers, 2018 to 2021). A group of at least three distinct histological types of lung cancer, including non-small cell squamous cell carcinoma, adenocarcinoma, and large cell carcinoma. "BCAT1 is commonly up-regulated in many different cancer lines, such as human glioblastoma, breast cancer, and non-small cell lung carcinoma (NSCLC), while BCAT2 seems more important for pancreatic cancer." (PMID 33669382, 2021).
pancreatic adenocarcinoma (2 papers, 2019 to 2023). "However, BCAT2 mediates decreased cell proliferation observed in pancreatic adenocarcinoma cell lacking mitochondrial malic enzymes 2 and 3 via its supply of glutamine for nucleotide synthesis." (PMID 31833233, 2019).
acne (1 paper, 2020). An inflammatory process of the sebaceous glands which is characterized by comedones, nodules, papules and/or pustules on the skin. "There were consistently 0 upregulated and 2 downregulated genes, including ACSBG1 and BCAT2, among GSE10432 (SEB-1 sebocytes incubated with isotretinoin for 72 hours), GSE10433 (acne patients treated with isotretinoin for 1 week), and GSE11792 (acne patients treated with isotretinoin for 8 weeks)." (PMID 32685503, 2020).
Acute encephalopathy (1 paper, 2023). "Mitochondrial BCAT2 mutations in N-ethyl-N-nitrosourea-treated mices produce pathological features similar to MSUD, providing an animal model for studying the metabolism of BCAAs, unlike MSUD, elevated plasma BCAAs in patients with BCAT2 deficiency do not lead to acute encephalopathy." (PMID 38028625, 2023).
benign prostatic hyperplasia (1 paper, 2025). A non-cancerous nodular enlargement of the prostate gland. "The results indicated that BCAT2 expression was lowest in benign prostatic hyperplasia and high-grade prostatic intraepithelial neoplasia, and progressively increased with the Gleason score." (PMID 40274762, 2025).
calcification (1 paper, 2026). Process by which organic tissue becomes hardened by the physiologic deposit of calcium salts. "Therefore, this study firstly found that targeting BCAT2 may be an effective method to treat diabetic atherosclerotic calcification, which is of great significance." (PMID 41503231, 2026).
Chorioretinal atrophy (1 paper, 2020). Atrophy (wasting) of the choroid and retinal layers of the fundus. "Other ophthalmological features that are seen in glutamate related disorders are optic atrophy in some GLS loss patients; herpetiform corneal ulcerations in patients with TAT deficiency; chorioretinal atrophy in OAT deficient patients; and retinal degeneration in BCAT2 deficient patients." (PMID 31603991, 2020).
chronic pancreatitis (1 paper, 2022). A chronic inflammatory process causing damage and fibrosis of the pancreatic parenchyma. "BCAT2 may potentiate acinar-to-ductal metaplasia (ADM), which is common in chronic pancreatitis and expedites the initiation of PanIN and facilitates adenocarcinoma." (PMID 35663242, 2022).
dementia (1 paper, 2022). Loss of intellectual abilities interfering with an individual's social and occupational functions. "Furthermore, isoleucine is a metabolite linked to genes involved in neurological disorders, such as dementia and seizures: BCAT1, BCAT2, and IARS2 (26980008 and 30098844)." (PMID 35629950, 2022).
Hyperglycemia (1 paper, 2023). An increased concentration of glucose in the blood. "As expected, the protein expression of BCAT2 and PP2Cm were higher in NAF1L2-deficient or SIRT3-activated CF than those of control cells in response to HG stimuli, indicating that the NAF1L2/SIRT3 pathway was involved in hyperglycemia-induced dysfunction of BCAA catabolism." (PMID 37993768, 2023).
Hyperleucinemia (1 paper, 2026). An increased concentration of leucine in the blood. "It is commonly believed that mutations in BCAT2 are associated with hypervalinemia and hyperleucinemia." (PMID 41457818, 2026).
invasive carcinoma (1 paper, 2022). A carcinoma that is not confined to the epithelium, and has spread to the surrounding stroma. "Among the genes involved in the initial 2 shared steps, the mRNA expression of BCAT2 and BCKDK was significantly higher, whereas the expression of PPM1K was lower, in the invasive carcinoma than that in normal breast tissue." (PMID 35785192, 2022).
myocardial ischemia (1 paper, 2022). A disorder of cardiac function caused by insufficient blood flow to the muscle tissue of the heart. "The BCAT1 and BCAT2 proteins highly ranking in KEGG results might play an important role in the regulation of metabolic pathway by RUS to improve myocardial ischemia." (PMID 35326233, 2022).
prediabetes (1 paper, 2024). "The lower expression of BCAT2 in the prediabetes group compared to normoglycemic individuals, as shown in our studies, suggests decreased activity of branched-chain-amino-acid aminotransferase (BCAT) in muscle." (PMID 39085321, 2024).
sarcopenia (1 paper, 2025). Progressive decline in muscle mass due to aging which results in decreased functional capacity of muscles. "2.In sarcopenia patients, the BCAT2 and BCKDHB genes involved in BCAA metabolism are significantly downregulated, and the levels of the key enzymes BCAT2 and BCKDHB are markedly reduced." (PMID 41568005, 2025).
cancer (33 papers, 2017 to 2026). A tumor composed of atypical neoplastic, often pleomorphic cells that invade other tissues. "Branched-chain amino acid aminotransferases (BCATs), existing as the two isoforms BCAT1 and BCAT2, are responsible for the catabolism of branched-chain amino acids (BCAAs) and are highly upregulated and implicated in a diverse range of cancers." (PMID 40005214, 2025). "BCAT1 is mainly involved in regulating the occurrence and development of cancer, while BCAT2 mainly plays a role in metabolic diseases." (PMID 41503231, 2026). "Branched-chain amino acid transaminases (BCATs), including BCAT1 and BCAT2, play pivotal roles in tumorigenesis and therapeutic resistance in various cancers." (PMID 41716286, 2026). "At the subcellular level, BCAT1 (cytosol, upregulated in many cancers) accelerates cytosolic transamination to generate glutamate and BCKAs, while BCAT2 (mitochondria) supports coupling of transamination to mitochondrial oxidation." (PMID 41502503, 2025). "BCAT1 is normally enriched in neural and germinal tissues but is ectopically expressed in various cancers, whereas BCAT2 is broadly expressed in adult tissues and resides in the mitochondria of many cell types." (PMID 41502503, 2025). "Isoform-Specific Contributions: How does BCAT1 versus BCAT2 overexpression differentially affect tumor metabolism and growth in distinct cancer contexts?" (PMID 40507232, 2025). "Recent studies have elucidated the role of BCAAs and BCAT2 in the pathogenesis of certain cancers, including pancreatic ductal adenocarcinoma (PDAC)." (PMID 40274762, 2025). "In support of this, a multi-omics study found that high BCAT2 expression in tumors correlated with reduced T cell infiltration and potentially higher levels of suppressive cells in some cancers." (PMID 41502503, 2025). "Translating BCAT2 inhibition to cancer means using it to push cancer cells into a metabolic corner—forcing them to either accumulate BCKAs or activate BCKDH and potentially overproduce ROS or deplete NAD+ (since BCKDH consumes NAD+)." (PMID 41502503, 2025). "A pan-cancer analysis of The Cancer Genome Atlas (TCGA) data found that BCAT2 gene amplification or overexpression is present in numerous tumor types and is often associated with worse survival." (PMID 41502503, 2025). "It was also demonstrated that BCAT2 in cancer cells reaminates branched-chain keto acids (BCKAs) supplied by cancer-associated fibroblasts into BCAAs." (PMID 38532464, 2024). "At last, predictive value of BCAT2 on response to immunotherapy was explored in various cancer types." (PMID 36642843, 2023). "In most of cancer types, the expression of BCAT2 is higher in cancer tissues than in normal tissues and its expression pattern in BLCA was validated in Xiangya BLCA Cohort." (PMID 36642843, 2023). "Through comprehensive pan‐cancer analysis, we found that BCAT2 has the most profound immunosuppressive effect in BLCA." (PMID 36642843, 2023). "What is worth affirming is that, at present, some patients have alleviated the development of cancer by targeting BCAT2 gene therapy; and achieved specific results." (PMID 36119495, 2022). "Underlining the role of ferroptosis during amino acid regulation in cancer, the induction of ferroptosis eventually inhibited transcription of BCAT2 and the direct inhibition of BCAT2 led to ferroptosis in target cells." (PMID 34926298, 2021). "In agreement with in vitro results, BCAT2 protected Panc02 cancer cells against erastin-induced reduction in tumor growth by twofold." (PMID 33097833, 2021). "In order to confirm the relationship between BCAT2 and ferroptosis in vivo, a subcutaneous xenograft tumor model was established by injecting 1 × 106 parental or overexpression BCAT2 Panc02 cancer cells into the C57BL/6 mouse." (PMID 33097833, 2021). "Of importance, BCAT2 has also shown the potential as a sensitive biomarker to evaluate drug responses in these preclinical cancer models." (PMID 33097833, 2021).